INS (insulin)
Diseases named in the same sentence as INS in open-access papers (continued):
Sharing a sentence is not in itself a finding about the gene and the disease.
diabetes (continued). "Furthermore, GLP-1 operates in a glucose-dependent manner, reducing the risk of hypoglycemia and stimulating the proliferation of insulin-producing β-cells, providing additional benefits for patients with diabetes." (PMID 30103438, 2018). "Importantly, our findings demonstrate that INS mutations leading to neonatal diabetes are already pathogenic during pancreatic development due to failure of neonatal beta-cell expansion." (PMID 30412052, 2018). "Diabetes is an epidemic chronic disease caused either by the failure of the pancreas in producing sufficient insulin or by the failure of the body cells in utilizing the insulin produced by the pancreas effectively." (PMID 29871651, 2018). "Insulin resistance, a condition often encountered in diabetes, is caused by the downregulation of all or part of the proteins involved in insulin signaling pathways, or by the inhibition (phosphorylation) of other signaling elements that inactivate the signaling pathways." (PMID 30602713, 2018). "Moreover, the Australian Diabetes, Obesity and Lifestyle study has also proposed that higher serum 25OHD levels were associated with improved insulin sensitivity, as assessed by HOMA-S." (PMID 29743959, 2018). "Exogenous insulin use in type 2 DM might reflect an advanced stage in the natural history of diabetes and could be associated with DPN by exacerbation of obesity, fluid retention, hypertension and hyperlipidemia." (PMID 29483946, 2018). "Hence, a disruption of insulin signaling along with AD pathology in brain regions controlling metabolism, such as the hypothalamus, can increase the susceptibility to diabetes and underpin the association of AD with T2D." (PMID 29945658, 2018). "The mechanism underlying the diabetes preventive ability of weight loss may be related to increased insulin sensitivity, thus delaying or preventing beta-cell failure." (PMID 29487293, 2018). "In their treatment guidelines, both the American Diabetes Association and the American Association of Clinical Endocrinologists confirm that insulin (either for initiation in patients with severe hyperglycemia or for treatment intensification) is the most efficient glucose-lowering agent." (PMID 30116737, 2018). "Regarding diabetes treatment, sulfonylurea and insulin were reported to cause hypoglycemia, which may explain the increased risk of hypoglycemia in the patients evaluated in the current study." (PMID 30355965, 2018). "The beneficial effect of higher 25(OH)D could be due to improving insulin sensitivity and anti-inflammatory effects [40, 41 although the exact mechanisms by which a higher 25(OH)D concentration lowers diabetes risk remain unclear." (PMID 29672520, 2018). "The phenylalanines and large aromatic residues function in insulin dimerization, negative cooperativity and receptor interaction, and their mutation produces diabetes (at human insulin Phe 24 and Phe25, the “insulin Los Angeles” and “insulin Chicago” syndromes)." (PMID 29892262, 2018). "Type 1 diabetes mellitus is a chronic autoimmune disease associated with degeneration of pancreatic β-cells that results in an inability to produce insulin and the need for exogenous insulin administration." (PMID 30586887, 2018). "Abnormalities such as altered insulin signalling, endoplasmic reticulum (ER) stress, mitochondrial dysfunction, and inflammation have been implicated in the pathogenesis of diabetes." (PMID 29484207, 2018). "The dysfunction and excess loss β-cells will result in a decrease of insulin, which may lead to hyperglycemia and diabetes." (PMID 30140229, 2018). "Therefore, ProINS-Tf is considered an ideal insulin analog for the treatment of insulin-deficient diabetes due to its liver-targeted effects." (PMID 29373562, 2018). "Interestingly, elevated UCP3 levels were observed in obesity-resistant mice and a decrease in UCP3 levels was associated with insulin sensitivity, a condition that precedes diabetes." (PMID 30295819, 2018).
diabetes (continued). "So, vitamin D deficiency may result in a decreased insulin release and insulin resistance and then contributes to the onset of diabetes." (PMID 29743959, 2018). "HOMA-β measurements, therefore, must be interpreted cautiously as high insulin secretion can suggest an individual is at risk of developing diabetes and low insulin secretion may suggest that the damage has already been done to the β-cell." (PMID 30473679, 2018). "Moreover, the development of diabetes-induced dementia is not only closely associated with hyperglycemia but also with the action of insulin." (PMID 29850612, 2018). "Diabetes mellitus (DM) is one of the most chronic metabolic disorders that occurs due to abnormal carbohydrate metabolism that is mainly linked with insensitivity of the target organs to insulin." (PMID 30235889, 2018). "In conclusion, the use of biguanides or thiazolidinediones may be associated with a low risk of NAF, whereas insulin may be associated with a significant increase in the risk of NAF in patients with type 2 diabetes mellitus during long-term follow-up." (PMID 30161122, 2018). "This increase in tissue oxidative stress may also be associated with diabetes or other changes in insulin levels." (PMID 30140168, 2018). "An outcome of the Fourth International workshop on the Standardization of Insulin Autoantibody Measurement, stated that: “Insulin autoantibodies measured by radioimmunoassay methodology are more related to insulin-dependent diabetes mellitus than those measured by Enzyme-Linked Immunosorbent Assay”." (PMID 29425252, 2018). "This could theoretically open up new possibilities for the treatment of mutant insulin-associated diabetes through transient stimulation of mTORC1, but this treatment would have to be applied within the neonatal period." (PMID 30412052, 2018). "Because these changes were associated with a decrease in insulin production, it was speculated that cellular senescence contributes to the pathogenesis of diet-induced diabetes." (PMID 30054761, 2018). "Many genetic variants are associated with increased diabetes risk, and some of these genetic variants reside in or near genes encoding voltage-gated K channels of pancreatic β-cells integral to glucose-stimulated insulin secretion." (PMID 30169531, 2018). "Thus, our aim was to evaluate the association of UGE with serum insulin levels and insulin resistance in subjects with glucose abnormalities, including prediabetes and newly diagnosed diabetes (NDD)." (PMID 30519194, 2018). "This includes the frequent observation that patients with type 1 diabetes in SSA tend to have delayed onset of type 1 diabetes compared to other settings and have a relatively higher presence of atypical variants of diabetes which require unique treatment regimens incorporating intermittent insulin." (PMID 30591044, 2018). "Further experiments could also start to address whether similar findings can be extended to insulin peptides that bind HLA class II, and in particular utilizing the diabetes associated DQ8 molecule." (PMID 29562882, 2018). "One interpretation that received quite some attention is that psychological factors, such as the burden of life with a chronic disorder and particular events in the disease course of diabetes (development of complications and start of insulin treatment), predispose diabetes patients to depression." (PMID 30135724, 2018). "Insulin deficiency in diabetes might have stimulated kidney tissues to make them more sensitive to insulin." (PMID 30602713, 2018). "Mutations which may be dominantly or recessively inherited from either parent or occur as a de novo mutation in a single gene affect the functioning of the insulin-producing pancreatic β-cells and precipitate a rare form of diabetes termed as monogenic." (PMID 29508275, 2018). "Therefore, we should clarify the molecular mechanism causing insulin resistance for development of fundamental treatments and prevention of diabetes mellitus." (PMID 30347717, 2018).
diabetes (continued). "Therefore, its reduction is considered an index of inadequate β-cell capacity to counteract the reduction in insulin sensitivity and a risk factor for future development of overt diabetes." (PMID 29925523, 2018). "Psychiatric medications are also known to cause cardiometabolic side effects including substantial weight gain, as well as adiposity-dependent and possibly adiposity-independent changes in insulin sensitivity and lipid metabolism, which increase the risk of diabetes and cardiovascular disease." (PMID 30255805, 2018). "UKPDS suggested that intensive blood glucose control with insulin could reduce risk of DR in newly diagnosed diabetes." (PMID 29854819, 2018). "It has been found that mutation in ZnT8 may contribute to dysregulation in insulin in the first passage through the liver and increase risk of type 2 diabetes mellitus development." (PMID 28965330, 2018). "The most commonly performed bariatric surgery procedures in the United States, sleeve gastrectomy and Roux-en-Y gastric bypass (RYGB), result in dramatic weight loss, improvements in peripheral tissue insulin sensitivity, and diabetes remission in a large percentage of patients." (PMID 30052546, 2018). "The use of this model at the first stage of experimentaldiabetology development enabled researchers to understand many aspects of themechanisms of insulin action, the metabolic changes related to insulindeficiency, and the pathogenesis of diabetes-associated disorders." (PMID 29713516, 2018). "Moreover, adjusted mean IGlar doses at 24 weeks for both groups were still below the limit for basal insulin titration (> 0.5 units/kg/day) recommended by the American Diabetes Association and European Association for the Study of Diabetes." (PMID 29760944, 2018). "Between the β-cell loss and ineffective insulin release and function lie other forms of diabetes." (PMID 29508275, 2018). "These values were similar to normal type values in this study, and thus, individuals with delayed insulin secretion, who might be at risk for diabetes, would have been overlooked in the healthy control group." (PMID 29629377, 2018). "Prep1/Pknox1 transcription factor has been widely investigated in our previous studies as an important regulator of metabolic homeostasis, as Prep1-deficient mouse model displays better insulin sensitivity and a reduced risk of developing diabetes and diabetes-related comorbidities." (PMID 29349576, 2018). "SERPINF2 modulates insulin sensitivity and is associated with cardiovascular diseases and diabetes." (PMID 29992704, 2018). "Complete OGTT information, such as 1-hour and 2-hour postloading plasma glucose and immunoreactive insulin levels, may be useful for predicting the future risk of diabetes or glucose metabolism disorders (GMD), which includes both diabetes and prediabetes." (PMID 30478026, 2018). "Thus, this work is aimed at evaluating the influence of insulin treatment on systemic mycosis caused by Paracoccidioides brasiliensis in a murine model of insulin deficiency (type 1 diabetes mellitus, DM1) induced by alloxan." (PMID 30426021, 2018). "In the current study, diabetes treatment intensity and especially insulin therapy was a marker of increased long-term risk for coronary revascularization, regardless whether catheterization was diagnostic only or resulted in PCI or CABG." (PMID 29402330, 2018). "Weight loss interventions such as diet, exercise, and insulin sensitizers and anti-androgens may decrease the risk of cardiovascular disease and progressive diabetes in patients with PCOS." (PMID 30647752, 2018). "Because beta cells in the pancreas produce lower insulin levels as diabetes progresses into later stage, if hyperinsulinaemia plays a key role in this association, stronger positive associations would be expected in the early stage of diabetes." (PMID 30401889, 2018).
diabetes (continued). "Diabetes mellitus is a metabolic disorder associated with an abnormal increase in blood glucose levels, perhaps due to defects in insulin secretions, and/or insulin action, and/or both, which is accompanied by one or more symptoms such as hyperglycemia, polyuria, polydipsia, and polyphagia." (PMID 30524684, 2018). "Furthermore, it has been shown that high circulating concentrations of insulin and C-peptide (a marker of pancreatic insulin secretion), and diabetes were associated with increased CRC risk." (PMID 30526552, 2018). "Consequently, insulin analogs for diabetes treatment can increase mitogenicity and risk of cancer, while manipulating IGF in the treatment of cancer can disrupt glucose homeostasis." (PMID 29892262, 2018). "As metabolic diseases including diabetes and obesity are associated with dysregulation of adrenal steroids, we postulated that metabolic hormones including insulin might directly influence adrenal steroidogenesis." (PMID 29567944, 2018). "To determine whether kaempferol is capable of reversing or ameliorating hyperglycemia following overt diabetes, we generated insulin deficient diabetic mice by injecting multiple low doses of STZ." (PMID 30216981, 2018). "Diabetes mellitus (DM) is a chronic metabolic disorder characterized by chronic hyperglycemia with impaired carbohydrate, protein, and fatty acid metabolisms arising from deficiencies in insulin secretion, action, or both." (PMID 30008637, 2018). "Diabetes mellitus is a type of metabolic disorders exhibiting high blood sugar level, caused by failure to produce enough insulin (type I diabetes) or failure to respond to insulin properly (type II diabetes)." (PMID 29912982, 2018). "Nevertheless, therapies demonstrating increased treatment satisfaction in T2D could be beneficial, particularly because insulin therapy for diabetes is associated with a high treatment burden and compliance issues." (PMID 29688502, 2018). "The term latent autoimmune diabetes in adults (LADA) has been introduced for this autoimmune diabetes characterized by adult onset, presence of diabetes associated autoantibodies and more frequent need for insulin treatment than patients with classical type 2 diabetes." (PMID 30346951, 2018). "These fatty acids could have beneficial effects on insulin sensitivity and is likely to reduce the risk of diabetes." (PMID 30513866, 2018). "We hypothesized that coadministration of glucagon and insulin could reduce the risk of hypoglycemia when treating diabetes." (PMID 29595915, 2018). "In this regard, treatment (and/or cure) of diabetes using TXNIP promoter linked with human insulin gene engineered into ASCs to make beta-like cells, which sense and produce insulin under high glucose is innovative and clinically applicable via subcutaneous transplant." (PMID 31355358, 2018). "PUFAs, similarly to monounsaturated FAs, may decrease oxidative stress, inflammation and endothelial dysfunction, influence both insulin secretion and insulin resistance, and reduce diabetes risk." (PMID 29452596, 2018). "Normally, approximately three-quarters of the total body glucose uptake stimulated by insulin is mediated by the skeletal muscles, and therefore, deficit of insulin or resistance of muscle fibers to insulin in diabetes mellitus causes changes in muscle energy metabolism." (PMID 30584460, 2018). "Briefly, smoking or exposure to cigarette smoke may decreased the adiponectin levels, thus, increased the insulin resistance and insulin levels, and this situation will increased the risk of diabetes mellitus in smokers and SHS exposure group." (PMID 30356972, 2018). "The strengths of this study include the use of the 2011 WHO diagnostic criteria, the use of OGTT as well as HbA1c as diagnostic tests for type 2 diabetes mellitus, and the ability to compare the strengths of the associations of incident diabetes with all three glycaemic measures as well as insulin." (PMID 29018885, 2018).
diabetes (continued). "In addition, dietary fiber has shown to reduce type 2 diabetes mellitus risk through glycemic control or decrease energy intake, reduce blood glucose excursions, and lower insulin responses." (PMID 30186541, 2018). "A reduction in insulin sensitivity represents a key hallmark of diabetes." (PMID 29531349, 2018). "However, it is notable that interventions that are known to be effective in preventing diabetes, including weight loss and treatment with insulin-sensitizing oral antidiabetic agents, also improve FFA and RQ in animal model." (PMID 30687238, 2018). "This may have important practical implications given the relatively large number of adult patients who are screened for GADA, both for diabetes classification and prediction of risk for insulin therapy." (PMID 29619531, 2018). "We also showed that SGLT2 inhibition decreases renal lipid accumulation and inflammation and prevents the development of nephropathy in db/db mice regardless whether they have insulin-deficient diabetes or insulin-resistant diabetes." (PMID 29301371, 2018). "Insulin regulation has been implicated in the pathogenesis of many of these diabetes traits." (PMID 29503662, 2018). "Significantly, our data demonstrated CPAE could protect pancreas from diabetes caused damages through improving pancreatic β-cell function and survival, eventually enhancing the synthesis of insulin, thereby decreasing blood glucose." (PMID 30140229, 2018). "Our study also demonstrated the significance of the miR199a-5p/ATG14 axis in translational diabetes research, which may serve as a potential therapeutic target for hepatic insulin sensitivity and other associated metabolic diseases." (PMID 29540751, 2018). "Since childhood diabetes and pre-diabetes status may have effects of vitamin D treatment on insulin sensitivity, we stratified the associations of VD2 treatment with WBISI and IGI by clinical diabetes measurements." (PMID 29641737, 2018). "Pancreatic islet transplantation as a therapeutic option for type 1 diabetes mellitus is gaining widespread attention because this approach can restore physiological insulin secretion, minimize the risk of hypoglycemic unawareness, and reduce the risk of death due to severe hypoglycemia." (PMID 30345316, 2018). "The best features, i.e. six biomarkers (adiponectin, C-reactive protein, ferritin, interleukin-2 receptor A, glucose, and insulin), were used in a PreDx diabetes risk score (DRS) model providing an AUC of 0.76 that increased to 0.78 when family history, age, BMI, and waist circumference were added." (PMID 28360826, 2017). "High levels of TNF-α may interfere with glucose metabolism and insulin sensitivity and increase the risk of new onset diabetes." (PMID 28813433, 2017). "This “double diabetes” may benefit from the addition of metformin to insulin and risk factor control, though clinical trials with vascular end-points are still awaited." (PMID 28948172, 2017). "Other factors significantly associated with development of diabetes in the present study were maternal age at delivery ≥ 30 years, birth weight of the index child >3.5kg and treatment with insulin during the index pregnancy after controlling for other variables." (PMID 28644881, 2017). "Diabetes mellitus (DM) type 1 is a metabolic disorder characterized by a severe deficiency in insulin secretion resulting from atrophy of the islets of Langerhans and causing hyperglycemia that results from a disruption of insulin-signaling because of insufficient insulin secretion." (PMID 29163175, 2017). "Notably, the decrease of insulin+MafA+ cells and the increase of insulin+MafB+ cells preceded the onset of diabetes, consistent with a causative role in hyperglycaemia, rather than a consequence thereof." (PMID 28598424, 2017).